CXCL8 (C-X-C motif chemokine ligand 8)
Diseases named in the same sentence as CXCL8 in open-access papers (continued):
Sharing a sentence is not in itself a finding about the gene and the disease.
tumor (continued). "EVs derived from NB cell lines have been demonstrated to affect BM-MSCs: they stimulated the secretion of tumor-supportive cytokines and chemokines from BM-MSCs in vitro, most notably IL-6, IL-8/CXCL8, vascular endothelial growth factor (VEGF), and CCL2/MCP-1." (PMID 33287630, 2021). "ROC curve analysis showed that CXCL8, DDX60, IFI44l, RSAD2, and RTP44 had better diagnostic efficiency for normal and tumor tissues, and the combined diagnosis was more effective." (PMID 34384424, 2021). "CXCL8 stimulates the proliferation and migration of vascular endohthelial cells to promote angiogenesis and tumor growth." (PMID 35011369, 2021). "CXCL8 promotes tumor progression through the STAT3 signaling pathway in head and neck squamous cell carcinoma." (PMID 35011369, 2021). "In conclusion, CXCL-8 concentrations have been suggested as potential biochemical tumor markers, particularly in the combined assessment with a well-established classical tumor marker for CRC–CEA." (PMID 34071492, 2021). "CXCR2 binds chemokines containing the glutamic acid-leucine-arginine (ELR) motif such as CXCL5 and CXCL8 that are involved in angiogenesis and also promote tumor progression." (PMID 34831316, 2021). "IL-6 and IL-8, encoded by the IL6 and CXCL8 genes respectively, are key cytokines involved in tumour growth, angiogenesis and metastasis." (PMID 34445479, 2021). "Tumor cells use chemokines to attract TANs to the tumor site, such as the potent neutrophil chemoattractant CXCL8, which entrains the CXCR1 and CXCR2 expression on neutrophils." (PMID 33936029, 2021). "Owing to the secretion of chemokines, namely, CCL2 and CCL5, TANs can recruit NK cells to the tumor site and, vice versa, NK cells attract neutrophils by secreting CXCL8." (PMID 34209508, 2021). "Model simulation and experiments consistently show that CXCL8 knockdown can reduce tumor growth and invasion." (PMID 33596197, 2021). "Krzystek-Korpacka showed that circulating CXCL8 was significantly elevated in ESCC patients and associated with tumor size, cancer dissemination, lymph node presence, and distant metastasis." (PMID 33390169, 2021). "CXCL8 activation by C/EBPδ is also in line with its role in promoting cancer stem cells and tumor progression." (PMID 34725321, 2021). "A pro-inflammatory cytokine response was shown to be elicited by PDT in HT29 tumor cells, as seen from the significant overexpression of the pro-inflammatory CXCL8 and IL1B genes in both adhered and detached cells." (PMID 34371724, 2021). "Meanwhile, we found that the concentrations of CXCL6 and CXCL8 in tumor tissue culture supernatants (TTCS) or tumor tissues were obviously augmented in contrast with those in non‐tumor tissue culture supernatants (NTCS) or non‐tumor tissues." (PMID 34185422, 2021). "A further study demonstrated that CXCL8 induced tumor-associated neutrophil and granulocytic MDSC extrusion of NETs, which shield tumor cells from contact with CD8+ T cells and limit the anti-PD-1 immune response to cancer." (PMID 35011369, 2021). "We compared the diagnostic utility of serum levels of CXCL-8 and CXCR-2 with classical tumor markers (CEA) for CRC." (PMID 34071492, 2021). "Human malignant cells can also produce CXCL8 to attract and retain DC to the tumor tissue that eventually decreases antitumor immunity." (PMID 35011369, 2021). "In support of this, analysis of the Gene Expression Omnibus (GEO) and TCGA databases showed significantly elevated levels of CXCL8 in HPV-negative compared to HPV-positive tumours, consistent with our in vitro 3D model data." (PMID 35047989, 2021). "Some chemokines, such as CCL2, CCL5, and CXCL8/IL-8, attract leukocytes and macrophages to the tumor site, where they can release vascular endothelial growth factor (VEGF) and other angiogenic factors that help new blood vessels form." (PMID 34943797, 2021).
tumor (continued). "Signaling of CXCR2 and its ligands (CXCL8 and CXCL1) leads to the recruitment of tumor-promoting immune cells, such as tumor-associated macrophages and MDSCs." (PMID 34944871, 2021). "Macrophages further favor the development of metastasis by inducing tumor cell invasion through the production of CXCL8 and osteopontin." (PMID 34572939, 2021). "For instance, it was found that the chemokines C-X-C motif ligand 1, 2, 3, and 8 (CXCL1, CXCL2, CXCL3, and CXCL8) are overexpressed in melanomas, which is accompanied by increased proliferation of tumor cells and tumor metastasis." (PMID 34885171, 2021). "Depletion of angiogenic factors, including VEGF, CXCL1 and IL-8/CXCL8, prevented tube formation mediated by these NK cells educated by the hypoxic cancer-derived EVs, showing that they all contributed to tumor-associated angiogenesis." (PMID 34944871, 2021). "In concordance with its primary role as a neutrophil attractant in inflammation, in a zebrafish model of glioma, CXCL8 was found to recruit neutrophils via CXCR1 to the tumor in the very early stages of development." (PMID 34503058, 2021). "CXCL8 is a member of the CXC chemokine family that acts as an important multifunctional cytokine to modulate tumor proliferation, invasion and migration in an autocrine or paracrine manner." (PMID 34126961, 2021). "This event was also closely associated with several potential chemotactic factors, among which CXCL8 (or IL-8) has been deemed as one of the most potent neutrophil chemoattractants with respect to tumour vascular biology." (PMID 33917287, 2021). "Postoperative infectious complications after esophagectomy have been related to tumor progression by developing inflammatory cytokines, such as CXCL8." (PMID 34640631, 2021). "Angiogenesis is also regulated by the local activity of a variety of other angiogenic factors, such as IL-8/CXCL8, a chemokine recognised as an angiogenic factor in several cancers and promoter of tumour growth, motility and metastasis." (PMID 34359570, 2021). "CXCL8 serum concentrations can accurately reflect the tumor burden of patients following antitumor therapy and have prognostic significance." (PMID 35011369, 2021). "Pulmonary infectious complications and anastomotic leakage have been related to tumor progression by developing inflammatory cytokines, such as CXCL8." (PMID 34640631, 2021). "In a mouse model of thyroid cancer, the treatment with thyroid-stimulating hormone increased the production of VEGF-A and CXCL8 from tumor cells resulted in the recruitment of F4/80+ macrophages and in supporting angiogenesis and tumor growth." (PMID 34209679, 2021). "VEGF secreted by cells in the tumor niche causes an increase in CXCL1 and CXCL8 expressions in endothelial cells, in a process important to angiogenesis and the migration of cancer cells." (PMID 33467722, 2021). "C-X-C motif ligand 8 (CXCL8) is a chemokine that acts as an important multifunctional cytokine to modulate tumor proliferation, invasion, and migration in an autocrine or paracrine manner." (PMID 34640631, 2021). "Neovascularization, which provides a basis for fostering tumor growth and metastasis, is now recognized as a critical function of CXCL8 in the tumor microenvironment." (PMID 34126961, 2021). "Similar findings were obtained when analyzing the expressions of CXCL6 and CXCL8 in tumor or non‐tumor tissues." (PMID 34185422, 2021). "In a study on epithelial tumor, CXCL8 plays a role in the acquisition and/or maintenance of the mesenchymal and invasive features of tumor cells." (PMID 32132577, 2020). "CXCL8 also activates MMPs, which degrade the basement membrane and extracellular matrix, promoting tumor cell migration, infiltration, and distant metastasis as well as angiogenesis within the tumor." (PMID 32456359, 2020). "Our findings indicated that following TNFα stimulation of tumor-stroma co-cultures, NF-κB activation has led to CXCL8 induction, partly through a Notch1-dependent process." (PMID 32582148, 2020).
tumor (continued). "Overall, our data demonstrated that p65-induced Notch1 activation was required for the contact-dependent induction of CXCL8 in the tumor-stroma-inflammation network, promoting malignancy-related function in TNBC cells." (PMID 32605277, 2020). "It was demonstrated that CXCL8 expression levels in tumor samples from GBM patients were significantly higher than in normal brain tissue and correlated with tumor progression." (PMID 32456359, 2020). "The TNFα-induced increase of tumor cell motility and CXCL8 production by contact TNBC co-cultures with MSCs were inhibited by GSI, and direct involvement of Notch1 was demonstrated in up-regulating CXCL8 production." (PMID 32605277, 2020). "Human cancers associated with high metastatic potential show constitutive expression of CXCL8, which enhances the development of metastases from primary tumours." (PMID 31986121, 2020). "Because IL-8 has been described to promote tumor cell survival, we started by analyzing mitotic apoptosis in either control cells or cells, in which CXCL8 was silenced." (PMID 32152317, 2020). "Tumors from CXCL8 overexpressing LNCaP cells exhibited increased tumor size, vasculature, and microvessel formation when compared to control cells, with CXCL8 overexpressing LNCaP cells also exhibiting enhanced invasiveness and MMP9 expression." (PMID 32585812, 2020). "Then, CXCL8 that was expressed at elevated levels played direct roles in promoting angiogenesis as well as tumor cell migration and invasion." (PMID 32582148, 2020). "Although M1 macrophages (classically activated) produce TNF-α, IFNγ, IL-12, and IL-23 and have pro-inflammation functions, M2 TAMs contribute to immune suppression, tumor growth, and metastasis via secretion of IL1β, IL-6, CXCL8, and VEGF." (PMID 32971847, 2020). "Among the various types of cytokines produced by tumor cells, interleukin-8 (IL-8, also known as CXCL8) was thought to alter leukocyte infiltration in the TME, thus resulting in the accumulation of pro-tumorigenic immune cells." (PMID 32296583, 2020). "An increased ratio of anti-apoptotic Bcl-2 family proteins, particularly Bcl-2 and Bcl-xL, to pro-apoptotic proteins Bax and Bcl-xs results in the increased tumor cell survival mediated by CXCL8." (PMID 32456359, 2020). "A contrasting study has shown that CXCL8 secreted by tumor cells activates proangiogenic and anti-apoptotic pathways by promoting the expression of VEGFA and bcl-2 at the invasion front, which confirms the key role of CXCL8 in tumor progression." (PMID 32201645, 2020). "One of the mechanisms by which some chemokines such as CCL2 or CXCL8 promote tumor growth and proliferation involves acting as autocrine or paracrine growth factors." (PMID 31991604, 2020). "The authors found significant CXCL-8 overexpression in CRC tissues which correlated with tumor size and depth of tumor invasion." (PMID 32192002, 2020). "Our study revealed that serum levels of CXCL-8, similarly to those of the classical tumor marker and CRP, were significantly higher in CRC patients in comparison to the healthy controls." (PMID 32192002, 2020). "The immunohistochemical study showed that the expression of CXCL8 was significantly upregulated as the number of infiltrating TAMs increased in the tumour tissues." (PMID 32201645, 2020). "Diagnostic sensitivity, predictive value of negative (NPV) results and accuracy were higher for serum concentrations of CXCL-8 in comparison to the classical tumor marker CEA." (PMID 32192002, 2020). "CXCL8 was mainly expressed in abnormal hyperplasia epithelium and carcinoma nests, and was rarely seen in tumour stroma." (PMID 32588946, 2020). "Then, CXCL8 has significantly contributed to elevated tumor cell migration and invasion, and also to increased angiogenesis." (PMID 32605277, 2020).
tumor (continued). "Despite continuing controversy regarding the relevance of CXCL-8 in cancer biology, our study revealed that CXCL-8 is a better biomarker than the currently-used classical tumor marker CEA in the diagnosis of CRC." (PMID 32192002, 2020). "The MDSCs are probably recruited and expanded in the tumor by cytokines such as CXCL8/IL-8 and IL-6, respectively." (PMID 32517213, 2020). "Strong CXCL8 expression was observed in the tumor tissue of high-grade tumors, while low-grade tumors had relatively lower expression levels." (PMID 32201645, 2020). "In colorectal cancer, CXCL8 recruits neutrophils into tumor site, which inhibits local immunity and in turn contributes to tumor development." (PMID 32632106, 2020). "CXCL8 exerts pleiotropic effects in cancer being involved in tumour cells proliferation, invasiveness, angiogenesis and inflammation." (PMID 31986121, 2020). "In parallel, inflammatory cytokines sustained the levels of CSCs, and recombinant IL-6 and CXCL8 increased the formation of tumor spheres by CD90+ tumor cells." (PMID 33585241, 2020). "Accumulating studies have revealed that CXCL8 is a critical component that involved in tumor initiation, promotion and progression." (PMID 32766720, 2020). "If we consider the relationship between the examined proteins and tumor stage, the highest concentrations of CXCL-8, CEA, and CRP were found in patients with stage IV cancer." (PMID 32192002, 2020). "For example, CXCL8 promotes tumor progression by increased infiltration of polymorphonuclear myeloid-derived suppressor cells (PMN-MDSCs)." (PMID 32971847, 2020). "Using a combination of human tissues, xenografts, syngeneic mouse models, and canine models of disease, they have shown how a ΔNp63/IL6/CXCL8 signaling axis mediates tumor-host signaling events critical to the metastatic process." (PMID 32082995, 2020). "Among the CXC ELR + chemokines, especially CXCL8 has been found to be important for tumor angiogenesis in several tumor types." (PMID 31690961, 2020). "CXCL8 also attracts chemotactic neutrophils to tumor sites and stimulates them to secrete various growth factors." (PMID 32456359, 2020). "Neutrophils can be recruited by CXCL8-secreting tumor cells and, in turn, modulate tumor growth by secreting the proliferation-inducing ligand APRIL and up-regulating the NF-kB, STAT3, and p38 pathways via the Toll-like receptor 9 signal." (PMID 32296632, 2020). "We performed a combined radiomics model that was composed of radiomics score, tumor stage, and CXCL8-derived radiomics model to make comparison with the clinical model." (PMID 33178604, 2020). "Interleukin 8 (CXCL8), CXCL3, and CXCL1 are CXC chemokines that are strongly associated with tumor angiogenesis." (PMID 32462020, 2020). "In our study, we observed that the expression of CXCL8 in HNSCC tissues was significantly upregulated when compared with non-tumor tissue." (PMID 33489879, 2020). "CXCL8 signaling has also been proposed to have a vital role in promoting tumor progression, by regulating apoptosis-related gene expression." (PMID 32766720, 2020). "Tumor-derived CXCL8 signaling can bias the tumor microenvironment toward immunosuppression through the transport of neutrophils and myeloid inhibitory cells [myeloid-derived suppressor cells (MDSCs)] with local resistance to antitumor immune responses." (PMID 33178604, 2020). "There were statistically significant differences in CXCL-8 concentrations between tumor stages, as established by the Kruskal–Wallis test and confirmed by the post hoc Dwass–Steele–Critchlow–Fligner test." (PMID 32192002, 2020). "Tumor-associated angiogenesis is driven by various cytokines including vascular endothelial growth factor (VEGF), CXCL8, IL-6, and TGFβ." (PMID 32585812, 2020). "Several studies indicated a pleiotropic role of CXCL8 in cancer due to its ability to modulate the tumour microenvironment, growth and aggressiveness of tumour cell." (PMID 31986121, 2020).
tumor (continued). "(C-X-C motif) ligand 8 (CXCL8) (also known as interleukin (IL)-8) is one of the proinflammatory chemokines produced by CRC cells at the tumor invasion front." (PMID 33276489, 2020). "Previous studies have revealed an abnormal high expression of CXCL8 in malignant tumors, which is mainly involved in tumor cell growth, apoptosis, invasion, and migration." (PMID 33178604, 2020). "CXCL8 has a tumor-supporting role by activating the epithelial-mesenchymal transition, promoting angiogenesis, and stemness potential." (PMID 33381115, 2020). "Neutrophil adhesion and chemotaxis were also activated, consistent with the well-known role of CXCL8 (IL-8) in the recruitment of neutrophils to the tumor site and in correlation with the increased proportion of TANs found in lesions compared to skin controls." (PMID 32664318, 2020). "Neutrophils have been reported to have the potential to promote tumor progression by establishing a tumor microenvironment, including a lot of inflammatory index, such as growth factors (CXCL8), proangiogenic factors (VEGF), and antiapoptotic factors (NF-κB)." (PMID 33293896, 2020). "On the contrary, one study suggested that neutralizing antibodies against CXCL8 exerted a partial inhibition of tumor growth and exhibited anti-angiogenesis activity in a nude mouse xenografts model." (PMID 32766720, 2020). "Various interleukins expressed by TAMs are also associated with tumor progression and prognosis, including IL-6, IL-10, CCL5, and CXCL8." (PMID 32268527, 2020). "In our study, significantly higher CXCL8 levels were found in metastatic ccRCCs compared to normal tissue, and a positive trend was observed in relation to tumor grade and stage in ccRCC patients." (PMID 30883740, 2019). "Now, in the presence of TNFα-induced signals, activation of p65 in the tumor cells has contributed much to CXCL8 release, and p65 activation in the MSCs provided its share as well." (PMID 31105691, 2019). "High levels of CXCL8 expression promote angiogenesis and attract neutrophils to release enzymes involved in tissue remodeling and tumor formation." (PMID 31788042, 2019). "The chemokines CXCL1, CXCL2, CXCL5, CXCL6, and CXCL8 secreted from tumor cells attract neutrophils in the blood to the tumor microenvironment via CXCR1 and CXCR2 on the surface of neutrophils." (PMID 30736371, 2019). "Neutrophils are part of the immune surveillance system that monitors and destroys transformed cells, and CXCL8 exerts an anti-tumor effect by recruiting concentrated granulocytes." (PMID 31788042, 2019). "In the tumor microenvironment, the inhibition of CXCL8 by different compounds (metformin, phenformin, interferons, AICAR,) was proved to exert beneficial anti-tumor effects." (PMID 31762942, 2019). "These considerations emphasize the relevance of the metastatic chemokines that are elevated due to the activity of the tumor-stroma-inflammation triage, particularly CXCL8, to therapy." (PMID 31031757, 2019). "Paradoxically, CXCL8 enhances the immune system response and increases its ability to execute anti-tumor effects, whereas it also transforms the tumor microenvironment to promote tumor growth." (PMID 31788042, 2019). "Significantly higher CXCL8 expression was found in metastatic ccRCC (n = 20; p = 0.0001) compared to normal tissue, and a positive trend was observed in relation to tumor grade and advanced stage in ccRCC patients." (PMID 30883740, 2019). "In our present study, we assessed the relationship between serum CXCL-8 levels and clinicopathological characteristics of the tumor." (PMID 30820705, 2019). "Evidence indicates, for example, that chemokines such as CCL5, CCL7, CXCL8 act via CCRs on myeloid-derived suppressor cells (MDSCs) to form an inhibitory tumor microenvironment that promotes tumor pathogenesis, progression and resistance." (PMID 30631005, 2019). "In a model of orthotopic TC xenograft in nude mice, CXCL8 was involved in tumor growth and progression." (PMID 31412566, 2019).